IL6 (interleukin 6)
Diseases named in the same sentence as IL6 in open-access papers (continued):
Sharing a sentence is not in itself a finding about the gene and the disease.
sarcoidosis (continued). "The synergistic effect of IL-1 and IL-6 was previously demonstrated to be a necessary factor for T-cell activation in sarcoidosis." (PMID 36388923, 2022). "To potentially address this unmet need, we evaluated a panel of markers for an association with sarcoidosis progression (HBEGF, NAMPT, IL1-RA, IL-6, IL-8, ANG-2)." (PMID 36388923, 2022). "While few cases showed the efficacy of anti-interleukin-6 (IL-6) or IL-6 receptor (IL-6R) agents in refractory sarcoidosis, new-onset sarcoidosis during TCZ treatment has been described in five case reports." (PMID 34359324, 2021). "Broncho-alveolar lavage fluid of sarcoidosis patients showed increased levels of exosomes inducing various pro-inflammatory cytokines, such as IL-1β, IL-6, and TNF (Tumor Necrosis Factor) alpha." (PMID 34440765, 2021). "Despite robust evidence on the role of IL-6 in the pathogenesis of sarcoidosis, data on the use of anti-IL-6 agents in sarcoidosis are scarce." (PMID 33330556, 2020). "Downregulation of HIF-1α via siRNA or chemical inhibitors in sarcoidosis PBMCs leads to a decrease in IL-6 and IL-17 production at baseline and in response to anti-CD3 stimulation." (PMID 30946009, 2019). "Previously, our group and other showed increased IL-6 production in AMs and PBMCs of sarcoidosis subjects at baseline and in response to TLR or NLR ligands." (PMID 30946009, 2019). "Significantly higher concentrations of secreted TNF and IL-6 were found in stimulated whole blood from patients with sarcoidosis compared with healthy controls." (PMID 27929051, 2016). "IL-6 production in response to SEA was significantly lower in blood from sarcoidosis patients, consistent with the T lymphocytopenia." (PMID 27929051, 2016). "After co-stimulation of PBMCs with FCWAs and LPS, the production of TNF-α, IL-6, IL-10 and IL-12 was significantly higher in patients with sarcoidosis, compared to healthy subjects (1.7-fold, 2.0-fold, 2.2-fold, and 2.8-fold, respectively; all p < 0.05)." (PMID 27688795, 2016). "When data from sarcoidosis and healthy subjects were pooled there was a trend towards an inverse correlation between IL-6 release and monocyte CD200R expression (r = 0.39, p = 0.21)." (PMID 27929051, 2016). "We demonstrated previously that after in vitro stimulation of PBMCs with FCWAs alone, the secretion of TNF-α, IL-6, IL-10 and IL-12 was higher in patients with sarcoidosis compared to healthy subjects." (PMID 27688795, 2016). "Monocytes are shown to be a source of TNF and IL-6 within stimulated whole blood assays, and monocytes from sarcoidosis patients produced these cytokines to a greater extent than healthy volunteers." (PMID 27929051, 2016). "Monocytes appeared to be responsible for elevated TNF and IL-6 responses in sarcoidosis patients, so monocyte subsets were characterised based on relative expression of CD14 and CD1624." (PMID 27929051, 2016). "In sarcoidosis, the proinflammatory cytokines interferon gamma, tumour necrosis factor and interleukin-6 are released by monocyte-derived macrophages and lymphocytes in the lungs and other affected tissues." (PMID 27929051, 2016). "In sarcoidosis, IL-6 responses were significantly higher in subjects with low monocyte CD200R expression when compared with high CD200R expressers, and a similar trend was observed for TNF." (PMID 27929051, 2016). "Of interest, IL-6 levels in the supernatants of cultured monocytes and alveolar macrophages have been reported to be significantly higher in patients with sarcoidosis than in controls." (PMID 25884809, 2015). "Additionally, among sarcoidosis patients experiencing disease progression, females expressed significantly higher IL-6 levels in their CD4+ T cells compared to males." (PMID 36899902, 2023). "However, there are also several cases published of paradoxical sarcoidosis onset in patients treated with anti-IL-6 agents for other disorders." (PMID 37841263, 2023). "In contrast, IL-6 was measurable only in 18% of sarcoidosis patients." (PMID 36207373, 2022).
sarcoidosis (continued). "Interestingly, higher serum IL-6, blood platelet count, and FVIII activity were independently associated with increased thrombin formation in sarcoidosis." (PMID 36494464, 2022). "IL1-β, TNF and IL-6 are all fundamentally associated with sarcoidosis, and CCL2 is a potent chemotactic agent for monocytes and T cells, and is strongly increased in BAL fluid of sarcoidosis patients." (PMID 32948789, 2020). "However, in the present study, IL-10 was selectively increased in IOL whereas bFGF, IFN-γ, IL-6, and IL-8 were also elevated in sarcoidosis, ARN, and BE." (PMID 32066796, 2020). "Previous reports showed increased IL-6 levels in the BALF of sarcoidosis patients." (PMID 33330556, 2020). "More IL-6 accumulation was also seen in sarcoidosis monocytes." (PMID 27929051, 2016). "We assessed whether the immuno-inflammatory signal observed in BAL cells of patients with sarcoidosis was also present in their BAL fluid by measuring protein levels of two differentially upregulated genes: IL6 and CCL5." (PMID 27460362, 2016). "However, the failure to demonstrate increased serum levels of IL-1β and IL-6 in sarcoidosis requires further investigation." (PMID 25866481, 2015). "Moreover, we observed a trend towards higher levels of MIG, IL-8, and IL-6, which were previously shown to be increased in sarcoidosis." (PMID 25366387, 2015). "Levels of IL-6 may be important in progression of fibrotic lung changes in sarcoidosis." (PMID 30946009, 2019). "Thus, in sarcoidosis increased IL-1β and IL-6 explains Th17 differentiation." (PMID 30946009, 2019). "Low monocyte CD200R expression was associated with heightened TNF and IL-6 production in response to PHA stimulation, and blockade of CD200R or CD200L in healthy controls led to increased TNF and IL-6 secretion by monocytes, recapitulating the hyper-activated monocyte state seen in sarcoidosis." (PMID 27929051, 2016). "Sarcoidosis patients had decreased levels of IL-1β, IL-5, IL-8, IL-12p70, TNF-α, angiogenin, C3a, C4a, RANTES, and MCP-1 and increased levels of IL-2, IL-4, IL-6, IL-13, IFN-γ, and VEGF." (PMID 40725075, 2025). "Based on our results, 9 possible biomarkers were identified (IL-1β, IL-6, IL-8, IL-13, VEGF, angiogenin, C4a, RANTES, and MCP-1) out of 18 tested that significantly differ in the BALF of patients with HP and sarcoidosis." (PMID 40725075, 2025). "This review further highlights the need for clinical trials to evaluate IL-6 blockade in disorders such neuropsychiatric lupus erythematosus (SLE), sarcoidosis and Behcet’s." (PMID 37841263, 2023). "Despite clinical remission, sarcoidosis was characterized by significantly higher concentrations of inflammatory markers, such as CRP, IL-6, and fibrinogen." (PMID 36494464, 2022). "They revealed several biological processes related to the pathogenesis of sarcoidosis, such as cellular response to IL-1 and interferon gamma (IFN-γ), regulation of IL-6 production, and response to lipopolysaccharide." (PMID 35860586, 2022). "Except for IL-8, plasma levels of each biomarker—eNAMPT, IL-1RA, IL-6, ANG-2, and HBEGF—were significantly elevated in sarcoidosis subjects compared to controls." (PMID 36388923, 2022). "We also found that the activity of other cytokines including GM-CSF (JAK2), IL-15 (JAK1/3), IL-6 (JAK1/2), IL-12 (JAK2/TYK2) and TNF (JAK-independent) are also evident in sarcoidosis." (PMID 35668129, 2022). "Bronchoalveolar lavage (BAL) cells from sarcoidosis patients produce more TNF-α and IL-6 in response to TLR2 agonists than healthy controls, while PBMCs from sarcoidosis patients had impaired TLR2 responses." (PMID 32256501, 2020). "Bronchoalveolar lavage (BAL) cells from patients with sarcoidosis produce more TNF-α and IL-6 in response to TLR2 agonists compared to healthy controls, while PBMCs from sarcoidosis patients have impaired TLR2 responses." (PMID 32722050, 2020).
sarcoidosis (continued). "Different pro-inflammatory cytokines such as interleukin (IL)-8, IL-12, IL-6, and tumor necrosis factor-alpha (TNF-α) have been shown to be highly expressed in sarcoidosis-affected tissues." (PMID 33330556, 2020). "Stimulated whole blood and monocytes from patients with sarcoidosis produced more TNF and IL-6 compared with healthy controls." (PMID 27929051, 2016). "The main results obtained from this study show that patients with sarcoidosis had a significantly higher secretion of inflammatory cytokines TNF-α, IL-6, IL-10 and IL-12 after in vitro co-stimulation of PBMCs with FCWAs and LPS." (PMID 27688795, 2016). "Our results showed that patients with sarcoidosis, compared to healthy subjects, had a significantly higher secretion of inflammatory cytokines TNF-α, IL-6, IL-10 and IL-12, after co-stimulation of PBMCs with FCWAs and LPS." (PMID 27688795, 2016). "This was attributed to production of the cytokines IL-6 and TNF at the site of inflammation; similar findings have also been reported for sarcoidosis." (PMID 25770018, 2015). "Cytokines integral to these reactions, like IL-6 and TNF-α, typically rise in chronic inflammatory diseases such as sarcoidosis, stimulating muscle protein degradation, retarding protein synthesis, and consequently invoking catabolic processes in muscle tissue." (PMID 39395132, 2024). "The majority of these SNPs were validated in AAs, with rs7549445, the top ranked SNP by p value, related to JAK1 gene, a Janus kinase, key component of the interleukin-6 (IL-6)/JAK1/STAT3 immune and inflammation response, supporting the importance of the JAK-STAT pathway in sarcoidosis." (PMID 38390497, 2023). "PTHrP immunoreactivity and/or mRNA in the cytoplasm of sarcoid macrophages and multinucleated giant cells were observed in more than half of lymph node biopsies in patients with sarcoidosis TNF-α and IL-6, may stimulate PTHrP production in sarcoid macrophages." (PMID 37358786, 2023). "It is also worth mentioning that drug-related sarcoidosis or sarcoidosis-like reactions have been reported in patients treated with immune-modulators, both PD1 inhibitors used in cancer treatment and anti-TNF or anti-IL6 drugs used in the treatment of CTDs and other systemic autoimmune diseases." (PMID 35441568, 2022). "Neither soluble TNF and IL-6 concentrations in plasma and BAL fluid nor IL-6-producing MNPs from BAL of sarcoidosis patients predicted disease outcome." (PMID 33446605, 2021). "Additionally, blood monocytes from sarcoidosis patients responded with higher TNF and IL-6 production after stimulation compared with controls." (PMID 33446605, 2021). "Typical findings are the lymph node enlargement found at CECT and, unlike sarcoidosis, the serum elevation of IL-6 levels." (PMID 32962242, 2020). "IL-6 is a potent up regulator of serum amyloid A protein (SAA), an acute phase reactant which has demonstrated a potential key role in the pathogenesis of sarcoidosis." (PMID 33330556, 2020). "Patients with sarcoidosis had a significantly higher secretion of inflammatory cytokines tumour necrosis factor-alpha (TNF-α), interleukin-6 (IL-6), IL-10 and IL-12 (1.7-fold, 2.0-fold, 2.2-fold, and 2.8-fold, respectively; all p < 0.05) after in vitro co-stimulation of PBMCs with FCWAs and LPS." (PMID 27688795, 2016). "Similar conclusions were also drawn by other authors, who found that peripheral blood mononuclear cells (PBMNC) isolated from sarcoidosis patients released higher amounts of various cytokines involved in the pathogenesis of sarcoidosis (such as IL-1β, TNF-α, IL-6, and GM-CSF), compared to controls." (PMID 26445225, 2015). "In the same way, many cytokines (including IL-1 receptor antagonist, IL-6, IL-8, IFN-γ, and TNF-α) and chemokines (IP-10, MIP-1α, MIP-1β, and RANTES) have been reported to be present in higher concentrations in the vitreous humor of eyes with sarcoidosis than that in those with ERM21,22." (PMID 32066796, 2020).
sarcoidosis (continued). "Plasma levels of eNAMPT, IL-6, ANG-2, IL-1RA, and HBEGF, but not IL-8 levels, were significantly elevated in sarcoidosis subjects compared to healthy controls." (PMID 36388923, 2022).
SARS-CoV infection (53 papers, 2005 to 2025). "There is other mechanism of infection related to SARS-CoV infection which is associated with high levels of cytokines, including interleukin (IL)-1β, IL-6, IL-12, interferon gamma (INFγ) and tumor necrosis factor-alpha (TNFα)." (PMID 33613024, 2021). "IL-6 has been shown to be induced in human bronchial epithelial cells following SARS-CoV infection in vitro and in vivo as well as associated with hyper-immune activation during SARS-CoV infection." (PMID 23029269, 2012). "SARS-CoV infection may lead to hyper-induction of the immune system, causing increased levels of cytokines, e.g., IL-6 and chemokines, all of which have been observed in SARS patients." (PMID 35678023, 2022). "Previous studies on severe acute respiratory syndrome (SARS) revealed the same pattern of increased concentrations of IL-6 in mildly affected patients, but the concentrations were significantly similar in control subjects." (PMID 39583156, 2024). "The fact that SARS-CoV infection triggers upregulated IL-6 in astrocytes is also intriguing, as astrocytic IL-6 has been shown to play a significant role in EAE development." (PMID 35572514, 2022). "In the murine nervous system, SARS-CoV infection triggers IL-6 expression by neurons and astrocytes, while SARS-CoV-2 triggers IL-6 expression by microglia in vitro, suggesting a potential role for IL-6 in neurological damage seen by coronaviruses." (PMID 35572514, 2022). "IL-6 and IL-8 releases are part of the cytokine storm, responsible for the Severe Acute Respiratory Syndrome (SARS)." (PMID 33494775, 2021). "Previously, higher expression of pro-inflammatory cytokine levels (IFN-α, TNF, IL-6, IL-8, IL-10, and IP-10) were described in monocyte-derived macrophages in SARS-CoV infections." (PMID 34539631, 2021). "Another study showed that the coding gene for hydroxysteroid 17-beta dehydrogenase 2 (HSD17B2) was downregulated in SARS-CoV infection, which is a consequence of stimulation of IL-1, IL-6, and TNFα as well as induction of inflammation." (PMID 32754004, 2020). "Similar to SARS-CoV infection, SARS-CoV-2 infection is associated with severe symptoms as well as higher IgM and IgG levels, which induce high IFN-γ, IL-6, TNF-α, and IL-10 secretion." (PMID 32627758, 2020). "In the early stages of SARS-CoV infection, cytokine levels in the blood, such as Il-6, Il-8, and TNF-α, are rapidly elevated, the elevation of which is associated with the progression of lung invasion and injury." (PMID 32754600, 2020). "IFNβ expression has been shown to be correlated with IL-6 expression during influenza virus infection and severe acute respiratory syndrome (SARS)-coronavirus infection, and IFNβ expression was also elevated in influenza virus-infected P58IPK−/− mice." (PMID 19461876, 2009). "During the process of SARS-CoV infection, there was a cytokine storm in patients including IL-1, IL-2, IL-4, IL-6, IL-8, IL-10, IFN-γ, TNF-α and TGF-β1." (PMID 18312678, 2008). "Similarly, patients with severe MERS-CoV and SARS-CoV infections showed higher levels of interleukin-6 (IL-6), a pro-inflammatory cytokine, and chemokines in their serum compared to those with mild disease." (PMID 32850602, 2020). "We found that genes such as IL6, Sh3gl3, and Atxn10, which had previously been associated with different phenotypic outcomes in response to IAV infection, also expressed different isoforms in response to SARS-CoV infection." (PMID 24902603, 2014). "As in SARS-CoV infections, the systemic levels of pro-inflammatory cytokine IL-6 was particularly associated with the severity of SARS-CoV-2 pathology and anti-IL-6 antibody therapy seems promising in early studies exploring its utility in the therapy SARS-CoV-2." (PMID 32850752, 2020).
SARS-CoV infection (continued). "IL-6 plays a variety of roles in regulating vascular leakage, complement activation, and the coagulation pathway, leading to adverse outcomes of acute respiratory distress syndrome, multiple organ dysfunction syndrome, and severe acute respiratory syndrome (SARS)." (PMID 33232275, 2020). "Differences in sequelae symptoms, cardiovascular biomarkers (VCAM-1, ICAM-1, and ACE2), Severe Acute Respiratory Syndrome Coronavirus 2 neutralization antibodies (SARS-CoV-2 nAb) and cytokines (IFN-γ, IL-6, and IL-17) were analyzed between the two groups." (PMID 39669584, 2024). "In a MERS-CoV infection, the epithelial and endothelial cells induced significant but delayed IFN and pro-inflammatory cytokine (IL-1β, IL-6 and IL-8) responses, while a large quantity of CCL3, CCL5, CCL2, and CXCL10 was produced during a SARS-CoV infection." (PMID 36016187, 2022). "SARS-CoV infection increases cytokine expression (e.g., IFN-γ, IL-1, IL-6, IL-10, IL-12, and IL-16) dramatically, and T lymphocytes and their CD4+ and CD8+ T cells subsets are decreased after the onset of infection." (PMID 33770147, 2021). "Abnormalities in the production levels of several cytokines such as IL-1, IL-2, IL-4, IL-6, IL-8, IL-10, IFN-γ, TNF-α and TGF -β1 were detected in patients with SARS-CoV infection." (PMID 32917282, 2020). "EBN also attenuated the surge in pro-inflammatory cytokines and chemokines such as TNF-α, CCL-2, NF-κβ, NO, IL-6, and increased IFN-γ, which are dysregulated in severe forms of IAV, and SARS-CoV infections." (PMID 34025406, 2021). "Another downregulated gene in the SARS-CoV infection is nitric oxide synthase traffic inducer (NOSTRIN) so this downregulation can induce the secretion of some proinflammatory chemokines and cytokines including CCL2, CCL5, and IL-6." (PMID 32754004, 2020). "Oxidized phospholipids that accumulate in HPAI and SARS-CoV infections also likely contribute to ALI and hypercytokinemia (“cytokine storm”) by signaling though toll-like receptor 4 (TLR4) and TRIF/TICAM1 in macrophages, activating NF-kB and inducing IL6." (PMID 30486363, 2018). "Similarly, DUSP8, IL6, CXCL10, and NFKBIA are up-regulated in SARS patients, while PTX3 and CXCL2 have been shown to be involved in SARS-CoV infection." (PMID 23935999, 2013). "We have reported that whereas human bronchial Calu-3 cells secreted high levels of biologically active IL-6, IL-8, and IP-10 in response to SARS-CoV infection, they failed to mount any detectable IFN-α/β response." (PMID 20090954, 2010). "Our studies indicate that protection from SARS-CoV infection correlates with MyD88-dependent induction of IL1-β, TNF-α, IL-6, MCP-1, MIP-1α, and RANTES at early times post infection and many of these cytokines/chemokines were upregulated in human SARS-CoV cases." (PMID 19079579, 2008). "The PBMCs from healthy individuals did respond to SARS-CoV infection by early (12 h) cytokine response, including the involvement of the master regulator NF-kB in the absence of pro-inflammatory cytokines TNF-α, IFN-γ, and IL-6." (PMID 32850752, 2020). "Since IL-6 signaling can drive further IL-6 expression via the RAS/MAP kinase cascade and NF-IL6 activation our results suggest that potentially self-sustaining acute phase responses occur during early SARS-CoV infection and not after reinfection." (PMID 23029269, 2012).